RN7SKP249 (RN7SK pseudogene 249)
Gene: Miscellaneous RNA gene on chromosome 8 (101,137,959 to 101,138,313, forward strand). Ensembl gene ENSG00000202360.
Homologues: Orthologues: chimpanzee 7SK (92% identical), guinea pig 7SK (55% identical). Paralogues in human: RN7SKP176 (67% identical), RN7SKP133 (66% identical), RN7SKP79 (66% identical), RN7SKP184 (66% identical), RN7SKP189 (66% identical), RN7SKP180 (66% identical), 7SK (65% identical), RN7SKP127 (65% identical), RN7SKP162 (65% identical), RN7SKP208 (65% identical), RN7SKP243 (65% identical), RN7SKP9 (65% identical), and 283 more.